MITF (melanocyte inducing transcription factor)
Diseases named in the same sentence as MITF in open-access papers (continued):
Sharing a sentence is not in itself a finding about the gene and the disease.
melanoma (continued). "Ultimately, we sought to investigate the potential of T. himalayense NIBRFG0000505337 as a whitening agent by assessing its impact on tyrosinase, TRP-1, TRP-2 and MITF expression in α-MSH-treated B16F10 melanoma cells and elucidating the underlying mechanism." (PMID 38480002, 2024). "Other common markers used to identify melanoma CTCs include microphthalmia-associated transcription factor (MITF)." (PMID 39156972, 2024). "The levels of MITF in melanoma are complex, but generally as described by the ‘rheostat’ model: higher levels of MITF are associated with differentiation and proliferation, whereas lower levels are associated with invasion and drug resistance." (PMID 39092608, 2024). "GDF6 was also linked to low levels of MITF, further demonstrating its ability to manipulate melanoma phenotypes." (PMID 38426087, 2024). "Microphthalmia-associated transcription factor (MITF) is a master regulator of melanocyte function, development and plays a significant role in melanoma pathogenesis." (PMID 39277608, 2024). "Melanoma cell lines harboring BRAF or NRAS mutations frequently showed low MITF levels and high AXL-RTK levels." (PMID 38672652, 2024). "At least one of these genes, TRIM63, is known to be strongly associated with melanoma, and is a validated target of MITF, the primary transcription factor controlling expression of pigmentation genes." (PMID 39294560, 2024). "Excluding mutations and other genetic alterations occurring in melanoma cells, the elevated number of intrinsic and microenvironmental factors contributing to MITF function modulation explains the intra- and inter-tumoral remarkable heterogeneity reported." (PMID 38473275, 2024). "Using data from melanoma patients, we observed that low levels of MITF expression are associated with decreased PRDX1 expression." (PMID 38790661, 2024). "For example, a recent study showed loss of MITF, encoding the microphthalmia-inducing transcription factor, in a melanoma cell line led to 2,136 genes being differentially expressed, of which 1,516 showed at least a 2-fold change in expression." (PMID 38141607, 2024). "It has also been reported that miRNA-137 harbours a melanoma susceptibility allele and is a down-regulator of MITF expression, apparently associated with cell cycle arrest in G1." (PMID 39594467, 2024). "While phenotype switching (EMT) and stem cell–like melanoma cells have been associated with NK cell evasion, other studies have found that melanoma cells expressing MITF, the master regulator of melanocytic differentiation, can also escape NK cell lysis." (PMID 36638181, 2023). "MITF activity is linked to melanoma cell phenotype and behaviour, where it mediates switching from highly proliferative to highly invasive states promoting tumorigenesis and metastases of the disease." (PMID 37752231, 2023). "MITF-low/AXL-high melanomas, characterized by low MITF expression and high AXL markers, are associated with intrinsic resistance to RAF/MEK inhibition therapy." (PMID 37239381, 2023). "Melanocortin 1 receptor (MC1R) and microphthalmia-associated transcription factor (MITF) are considered moderate-penetrance melanoma genes." (PMID 37958811, 2023). "This diversity in MITF response and its involvement in melanoma survival led us to explore any causal relationship with the observed differential susceptibility to T cell-induced cytotoxicity." (PMID 36812891, 2023). "We have demonstrated that uridine breakdown is promoted by MITF, a transcription factor associated with melanoma progression, which we show binds upstream of UPP1 to promote its expression." (PMID 37198474, 2023). "This aggressive melanoma phenotype shows low MITF and high AXL expression, which causes early metastasis through pro-angiogenic factors such as VEGF and interleukin-8 (IL-8)." (PMID 36675114, 2023).
melanoma (continued). "These mutations can inhibit the expression of a transcription factor called microphthalmia-associated transcription factor (MITF) in the TME of melanoma." (PMID 37221594, 2023). "We modeled BRAFV600E and NRAS-mutant tumors, which form most patient cutaneous primary melanomas in the clinic, and considered a range of further molecular alterations, namely, MITF status, loss of PTEN, presence of BRAFV600E, and loss of CDKN2A." (PMID 37043573, 2023). "MITF is well known as a key molecule in melanocyte biology as well as functioning as an oncogene that is amplified and mutated in sporadic melanomas." (PMID 36672892, 2023). "This, in turn, exerted an adverse tumor-protective effect on melanoma by preventing microphthalmia-associated transcription factor (MITF) downregulation." (PMID 37626777, 2023). "Microphthalmia-associated transcription factor (MITF) is an important regulator in melanoma development and progression." (PMID 37239381, 2023). "Research has shown that AXL expression is associated with melanoma dedifferentiation, whereas MITF expression is linked to differentiated tumors." (PMID 37259155, 2023). "There is also a study indicating that microphthalmia-associated transcription factor (MITF) inhibitor CH6868398 sensitized melanoma cells to BRAF kinase inhibitor." (PMID 36834830, 2023). "SAMMSON is colocalized with MITF and the amplification of both genes in approximately 10% of melanomas has been associated with poor prognosis." (PMID 37325482, 2023). "In fact, it is well known that low levels of MITF are linked to senescence and invasion, while high levels of MITF are linked to the proliferation and differentiation abilities of melanoma cells." (PMID 37627054, 2023). "Here we show, using melanoma as a model, that the microphthalmia-associated transcription factor MITF, a lineage addition oncogene that coordinates many aspects of melanocyte and melanoma biology, plays a non-transcriptional role in shaping the DDR." (PMID 37131595, 2023). "Amplification in MITF is present in about 20% of melanomas and is associated with reduced five-year survival." (PMID 37762707, 2023). "They found that a TME in which cancer-associated fibroblasts (CAFs) were highly abundant was associated with an invasive phenotype (microphthalmia-associated transcription factor (MITF)-low/AXL-high) of melanoma cells." (PMID 38139110, 2023). "The treatment with acriflavine resulted in the passing of melanoma cells due to a suppression of the microphthalmia-associated transcription factor (MITF)." (PMID 36831579, 2023). "In melanoma, MITF has been implicated in regulating many biological processes including reprogramming metabolism, promoting survival, proliferation, differentiation and autophagy, and suppressing invasion and senescence." (PMID 37770430, 2023). "One study reported that low MITF expression levels were associated with resistance to chemotherapy in melanoma cell lines." (PMID 37504268, 2023). "Other known lineage-specific oncogenes include SOX2 in lung and oesophageal squamous cell carcinomas, and MITF (microphthalmia-associated transcription factor) in melanoma." (PMID 37752235, 2023). "MITF down regulation causes invasive dedifferentiated melanoma, while overexpression causes a proliferative phenotype." (PMID 36747120, 2023). "Among the most well-characterized molecular changes that signify a shift in melanoma cell behavior, linked to phenotypic plasticity, and acquisition of migration and invasion, is alterations in the expression level of MITF." (PMID 36675114, 2023).
melanoma (continued). "Here, we show that the expression of the GREB1 splicing variant, isoform 4 (Is4), is mediated by MITF in melanoma cells." (PMID 37658191, 2023). "Impaired translation is accompanied by an amino acid deprivation-dependent stress response driving activating transcription factor-4 (ATF4)high/microphtalmia-associated transcription factor (MITF)low transcriptomic signatures, also in patient melanomas." (PMID 36812891, 2023). "Microphthalmia-associated transcription factor (MITF) has been reported to be a susceptible gene in melanoma families and the general population." (PMID 36901857, 2023). "Upregulation of POU3F2 represses Microphthalmia-associated transcription factor (MITF) expression in some melanomas by binding to its promoter region, which drives the cells to adopt a more stem-like and aggressive phenotype." (PMID 35546872, 2022). "Enrichment analysis showed that melanoma profiles previously found to be associated with high levels of MITF activity were enriched for genes directly activated by TFAP2, including the subset associated with TFAP2-dependent MITF peaks." (PMID 35580127, 2022). "Taken together, Wnt/β-catenin signaling deficiency exacerbates ferroptosis in melanoma via the regulation of MITF." (PMID 36429010, 2022). "Transient MGRN1 depletion with siRNA or permanent knockdown in human melanoma cells by CRISPR/Cas9 caused an apparently MITF-independent switch to a more dendritic phenotype." (PMID 35892921, 2022). "Although MITF expression is highly variable across melanoma specimens, its amplification is directly implicated in metastatic melanoma and identified as a prognostic marker for survival." (PMID 36499416, 2022). "Our results validate at protein level that loss of MITF in melanoma cells specifically is a marker of aggressive disease, as previously shown only at transcriptional level." (PMID 36040798, 2022). "In melanoma, loss of microphthalmia-associated transcription factor (MITF), the master regulator of melanocyte differentiation, is associated with the reactivation of neural crest progenitor genes and leads to invasive tumors." (PMID 36230781, 2022). "An essential role for glutamine deprivation in melanoma was suggested to suppress MITF, promote invasion, and upregulate genes associated with EMT." (PMID 35406721, 2022). "Our study shows that SOX10-deficient melanoma cells are slow-cycling, which is an effect associated with reduced expression of MITF and cyclin D3 as well as enhanced p21Cip1." (PMID 35296667, 2022). "A second transcriptomic signature that has been associated with the melanoma cell phenotypic switch that is inversely correlated to MITF expression, is the expression of the receptor tyrosine kinase AXL." (PMID 36119516, 2022).
melanoma (continued). "In a considerable fraction of human melanomas, Microphthalmia‐associated transcription factor (MITF) is regarded as an oncogene and plays a key role in tumour progression." (PMID 35452181, 2022). "High MITF levels are thought to promote cell proliferation through the direct activation of the DIAPH1 gene, and low MITF expression in melanoma is associated with cell migration." (PMID 36248850, 2022). "Such tumors were larger, underlining a possible cooperation between MITF– and MITF+ melanoma cells and the tumor microenvironment in vivo." (PMID 36040798, 2022). "Instead, low MITF together with Notch signaling is linked to immune infiltration in both mouse and human melanoma tumors." (PMID 35771179, 2022). "Key to understanding phenotype‐switching in melanoma is the microphthalmia‐associated transcription factor MITF, first identified because of its critical role in promoting survival of migrating melanoblasts in development." (PMID 35771179, 2022). "The NCSC-like melanoma cells express the transcription factor SOX10, while the undifferentiated melanoma cells have concomitant loss of MITF and SOX10." (PMID 36040798, 2022). "Mucosal melanomas tend to have increased copy numbers of genes critical for pigment development, such as MITF, which, when mutated, can make cancers resistant to treatment." (PMID 35406524, 2022). "More specifically, changes in the expression of the master regulator microphthalmia-associated transcription factor (MITF) has been associated with melanoma phenotypic switching." (PMID 36119516, 2022). "The initiation of p16INK4A by the MAPK pathway along with activation of microphthalmia-associated transcription factor (MITF) locus amplification is found in 20–30% of melanomas." (PMID 36135270, 2022). "Histone H3 acetylation at the level of 27 lysine residue (H3K27ac) is an important regulator of MITF (melanocyte inducing transcription factor) expression and is associated with an increased metastatic potential to melanoma cells." (PMID 36614156, 2022). "Heterogeneous expression of microphthalmia-associated transcription factor (MITF) has been observed extensively in melanoma development and progression." (PMID 35740696, 2022). "BRAF-activated melanomas are characterized by a suppressed level of microphthalmia-associated transcription factor (MITF) and thus a low PGC-1α expression, which leads to attenuated mitochondrial function." (PMID 36003368, 2022). "The SAMMSON gene is co-amplified in melanomas together with MITF within the genomic locus 3p13-3p14 and is associated with poor prognosis in melanoma patients." (PMID 35159386, 2022). "These methods have been applied recently to discover melanoma predisposition genes such as MITF, TERT and POT1." (PMID 35085295, 2022). "Melanomas with low MITF expression have previously been associated with an aggressive phenotype in vitro and in vivo." (PMID 36040798, 2022). "Here, we demonstrated that SMILE expression markedly decreased in human melanoma biopsy specimens and was inversely correlated with that of microphthalmia-associated transcription factor (MITF)." (PMID 36499416, 2022). "MITF is one of the universal diagnostic markers of cutaneous melanoma based on its expression in most melanoma cells." (PMID 35929478, 2022). "In melanoma cell lines, microphthalmia-associated transcription factor (MITF) activated SDHB expression and inhibited succinate accumulation and the consequent stabilization of HIF." (PMID 36551845, 2022). "Acute MITF loss can sensitize cells to tumor necrosis factor α (TNFα), a key inflammatory signal that is implicated in melanoma de differentiation and resistance to adoptive T‐cell therapy." (PMID 35771179, 2022). "The biological processes associated with high or low MITF activity within the TCGA melanoma cohort were revealed using the Kyoto Encyclopedia of Genes and Genomes (KEGG) pathway analysis." (PMID 35771179, 2022).
melanoma (continued). "In previous studies, the deregulation of MITF is known to cause skin diseases such as hyperpigmentation, melasma, and melanoma." (PMID 36613979, 2022). "Melanoma cells can switch between different MITF-associated states: MITFhigh, a highly proliferative and differentiated albeit less invasive state; and MITFlow, which is less proliferative, dedifferentiated, and highly invasive." (PMID 35267510, 2022). "MITF is considered a master transcriptional regulator of pigmentation; in addition, melanocytic differentiation, mutations, and aberrant expression of MITF are associated with skin pigmentation abnormalities and melanoma in both mouse models and humans." (PMID 36499416, 2022). "This variant was initially linked to RCC in a study of individuals with RCC, and malignant melanoma and functional studies of this variant demonstrated MITF upregulation through loss of a SUMOylation site." (PMID 35441217, 2022). "If so, MITF mRNA expression should broadly relate to previously determined melanoma‐associated proliferative or invasive gene expression signatures that are inversely correlated in the 473 tumor samples in the TCGA melanoma cohort." (PMID 35771179, 2022). "The sensitivity of melanoma cells to BRAFi has been associated with a highly differentiated cell state under the control of the MITF transcription factor (i.e., MITFhigh or pigmentation signature)." (PMID 36305167, 2022). "In summary, transient depletion or permanent ablation of MGRN1 in human melanoma cells caused an apparently MITF-independent switch to a more dendritic phenotype, consistent with previous observations in mouse melanocytes." (PMID 35892921, 2022). "In melanoma, a key determinant of phenotypic identity is the microphthalmia‐associated transcription factor MITF that promotes proliferation, suppresses senescence, and anticorrelates with immune infiltration and therapy resistance." (PMID 35771179, 2022). "Additional bioinformatics studies also suggested an association between YY1 and MITF in melanoma progression." (PMID 35719931, 2022). "The two phenotypes first described in melanoma are the invasive, characterized by slow proliferative rate and low MITF levels; and the proliferative, associated with high proliferation and MITF levels." (PMID 35075772, 2022). "MITF, widely identified as one of the most classic and pivotal regulators in malignant melanoma, has been associated with phenotypic switching between predominantly invasive and proliferative behaviours of melanoma." (PMID 36268034, 2022). "Bioinformatic analyses of melanoma gene expression datasets revealed different subsets of BRAF/NRAS melanomas that differ in the endogenous expression of MITF independently of the oncodriver mutation." (PMID 35580987, 2022). "In this study, we determine the functional and transcriptional phenotypes of melanoma cells with retained or loss of MITF and SOX10 expression, respectively." (PMID 36040798, 2022). "Of note, genes downregulated by TFEB knockdown are significantly associated with the gene set regulated by MITF in melanoma cells." (PMID 36372230, 2022). "Kojic acid is only known to inhibit melanogenesis by direct inhibition of tyrosinase; however, it does not affect the expression of microphthalmia-associated transcription factor (MITF), which is engaged in proliferation and survival of melanoma cells." (PMID 34072104, 2021). "BRAFi treatment causes melanoma cells to change their MITF expression to low or high levels, both of which lead to slowly proliferating resistant cells." (PMID 33840166, 2021). "In turn, this process leads to microphthalmia-associated transcription factor (MITF)-mediated skin melanogenesis in UVB-irradiated murine melanoma cells." (PMID 34082382, 2021).